IQGAP3 (IQ motif containing GTPase activating protein 3)
Diseases named in the same sentence as IQGAP3 in open-access papers (continued):
Sharing a sentence is not in itself a finding about the gene and the disease.
tumor (continued). "However, in contrast to IQGAP1 and IQGAP3, which were suggested to be oncogenes, IQGAP2 was implicated to be a putative tumor-suppressor gene." (PMID 32824461, 2020). "Immunohistochemical expression of IQGAP3 in tumor tissues was observed in the cytoplasm with different intensities, with 61 cases showing low expression (20% IQGAP3) and 57 cases showing high expression (70% IQGAP3)." (PMID 31223291, 2019). "So far no studies have been found demonstrating the relationship between IQGAP3 and CRC, our findings may verify the role of IQGAP3 played in tumorigenesis and tumor progression, and can further clarify the prognostic value of IQGAP3 in CRC patients." (PMID 31223291, 2019). "In addition, IQGAP3 urinary NA levels were significantly higher in BCpatients at all tumor grades (PicoGreen-adjusted: (all,P<0.001) and RiboGreen-adjusted: G1(P=0.002), and G2 and G3 (P<0.001))than in hematuria controls." (PMID 29581849, 2018). "Moreover, a 3D spheroid invasion assay, which is considered a good simulation of tumor invasion in vivo, revealed that IQGAP3-overexpressing cells exhibited active invasive behaviors, characterized by the formation of outward projections from individual cells." (PMID 28810875, 2017). "They showed that overexpression of IQGAP3 promoted tumor cell growth, migration and invasion." (PMID 29073199, 2017). "Therefore, IQGAP3 may potentially facilitate tumor immune evasion by stimulating the intricate interactions between cellular immune components and immune-infiltrating cells." (PMID 38560572, 2024). "In addition, the role of IQGAP3 in immunotherapy and targeted therapy may shed light on future tumor therapy." (PMID 36164370, 2022). "Interestingly, the expression level of IQGAP3 increased as the patient's tumor stage increased." (PMID 36164370, 2022). "Therefore, we speculate that IQGAP3 may further affect tumor progression by affecting the tumor immune microenvironment." (PMID 36164370, 2022). "In addition to IQGAP3, a host of tumor markers have been detected and used in clinical practice." (PMID 31223291, 2019). "Therefore, whether the different expression pattern of IQGAP3 suggests a more confound regulation and function of IQGAP3 in tumor development needs further studies." (PMID 24849319, 2014). "IQGAP3 and IQGAP1 activate ERK-related cell proliferation and function as oncogenes, while IQGAP2 tends to inhibit tumor progression." (PMID 40634295, 2025). "Normal tissues exhibited higher levels of S100A9, FTCD, POF1B, IL7R, and MYO1E, whereas tumor tissues showed increased expressions of SPINK1, CXCL9, AGFG1, and IQGAP3." (PMID 41578779, 2025). "IQGAP2 and IQGAP3 are both correlated with the MAPK/ERK pathway, which is one of the most crucial signaling pathways in the progression of cancer, promoting tumor growth and metastasis." (PMID 36831467, 2023). "After analyzing the single-cell dataset, it was discovered that IQGAP3, KIF4A, and WASIR1 were expressed in immune cells, indicating their potential involvement in regulating the tumor immune microenvironment in PCa." (PMID 37370891, 2023). "The current research focused on the role of IQGAP3 and KIF4A in the tumor development process; nonetheless, how these molecules affect the response to ICI treatment at the molecular level must be elucidated at a later stage." (PMID 37370891, 2023). "The expression of IQGAP3 in 27 pair (Series: GSE66272) and 72 pair (Series: GSE53757) of ccRCC tumor tissues and matched normal tissues at different disease stages were extracted and analyzed." (PMID 36275458, 2022). "Surprisingly, majority of these studies suggest that IQGAP3 modulates tumorigenesis by regulating the EMT and thus controlling tumor metastasis." (PMID 35355828, 2022). "The results showed that the patients in tumor tissues with high IQGAP1 expression, low IQGAP2 expression, and high IQGAP3 expression had the shortest survival time, which is consistent with our findings." (PMID 36320006, 2022).
tumor (continued). "IQGAP2 has been proposed to be a tumour suppressor and its expression is downregulated when IQGAP1 is overexpressed in hepatocellular carcinoma, while IQGAP3 shows oncogenic properties." (PMID 33672268, 2021). "Univariate analysis showed that tumor size, T stage, N stage, differentiation degree, TNM stage, both serum and tissue IQGAP3, B7-H4 and COX-2 levels and serum CEA and CA19-9 levels were significant prognostic factors for CRC." (PMID 31223291, 2019). "Immunohistochemistry was performed to detect the IQGAP3, B7-H4 and COX-2 in tumor tissues and normal para-carcinoma tissues." (PMID 31223291, 2019). "CCT3 and IQGAP3 protein level correlated well with HCC etiology, tumor size, TNM stage, and child-pugh classification." (PMID 27390551, 2016). "In this work, we found that concentration of serum CCT3 and IQGAP3 in patients with HCC was correlated with etiology, tumor size, number of cancer nodules and child-pugh classification, indicating that they are novel predictors for HCC." (PMID 27390551, 2016). "An inter-chromosomal rearrangement occurred between chromosome 17 and chromosome 1 was identified in patient WG04, in both primary and metastasis tumours, which results in a novel gene–gene fusion involving TMC6 and IQGAP3, with reversed 5′ and 3′ orientation." (PMID 26647728, 2015). "The AL040372-specific sequence corresponding to the tumor-related transcript of interest is mapped to the 3'-terminal intron and the 3'-UTR of IQGAP3 mRNA." (PMID 17189608, 2006). "Conversely, the upregulated gene subset (e.g., SIM2, HJURP, IQGAP3, KIF18B) showed predominantly negative correlations with many IRGs, potentially reflecting an association with the suppression of anti-tumor immune responses." (PMID 41439026, 2025). "Both IQGAP1 and IQGAP3 are considered oncogenes in HCC and, thus, can serve as highly sensitive and specific biomarkers for this type of tumor, while IQGAP2 may act as a tumor suppressor." (PMID 36559011, 2022). "Next, we checked the expression levels of IQGAP3 using qRT-PCR and found significantly high levels of IQGAP3 in the tumor samples compared to the adjacent nontumor samples." (PMID 35355828, 2022). "IQGAP3, B7-H4 and COX-2 these three tumor markers were compared in three groups." (PMID 31223291, 2019). "The oncogene IQ motif-containing GTPase activating protein 3 (IQGAP3) is ubiquitously overexpressed in several human cancers, including liver, ovary, lung, large intestine, gastric, bone marrow, and breast malignancies and is involved in the invasion and metastasis of cancer cells." (PMID 28810875, 2017). "The significance of such selectivity remains to be determined, however we speculate that IQGAP1 and IQGAP3 may cooperate in regulation of ERK signaling, thereby exerting a synergistic effect on tumor progression." (PMID 24849319, 2014). "However, we did not observe differences in the expression of IQGAP3 between cancer stages, nodal metastasis stages, and tumor grades." (PMID 32824461, 2020). "However, the potential role of IQGAP3 in various tumor types has not been fully elucidated." (PMID 36164370, 2022). "Furthermore, IQGAP3 functions as an important regulator of metastasis and EMT by constitutively activating the TGF-beta signaling pathway; hence, it may also play some roles in promoting cancer stemness through regulation of tumor microenvironment." (PMID 32824461, 2020). "Analysis of the mRNA expression of IQGAP3 in HCC tissues showed that IQGAP3 levels remained low in non-tumor liver tissues, but increased significantly in patients with HCC (P < 0.0001), suggesting that IQGAP3 might contribute to the high cell-proliferation rates in HCC." (PMID 28810875, 2017). "Multivariate analysis indicated that multiple tumor numbers, positive IQGAP1, negative IQGAP2, and positive IQGAP3 expressions were independent prognostic factors for RFS." (PMID 36320006, 2022).
tumor (continued). "Multivariate analysis indicated that multiple tumor numbers, advanced TNM stage, positive IQGAP1, negative IQGAP2, and positive IQGAP3 expressions were independent prognostic factors for OS." (PMID 36320006, 2022). "Univariate analysis showed that larger tumor size, multiple tumor numbers, microvascular invasion, poor tumor differentiation, advanced TNM stage, positive IQGAP1, negative IQGAP2, and positive IQGAP3 expressions were prognostic factors for RFS." (PMID 36320006, 2022). "IQGAP3, B7-H4 and COX-2 showed low or high expression in tumor tissues while no expression in normal para-carcinoma tissues." (PMID 31223291, 2019). "Besides, univariate analysis showed that multiple tumor numbers, microvascular invasion, poor tumor differentiation, advanced TNM stage, positive IQGAP1, negative IQGAP2, and positive IQGAP3 expressions were prognostic factors for OS." (PMID 36320006, 2022).
cancer (37 papers, 2014 to 2025). A tumor composed of atypical neoplastic, often pleomorphic cells that invade other tissues. "The protein encoded by IQGAP3 belong to the Rho family, which play critical roles in the development and progression of several cancers." (PMID 40324248, 2025). "In most cases, IQGAP3 is associated with increased cell proliferation and was found to be overexpressed in various types of cancers." (PMID 38674130, 2024). "Our future research will encompass a broader range of animal models and clinical samples, employing molecular biology experiments to elucidate further the relationship between IQGAP3, genetic mutations, and cancer signaling pathways." (PMID 38560572, 2024). "In this review, we comprehensively reviewed the significant roles of IQGAP2 and IQGAP3 in cancer-associated pathways as well as the role in carcinogenesis and progression of different cancer entities." (PMID 36831467, 2023). "This is the first study to characterize the expression, prognosis, DNA methylation, and gene mutation of IQGAP3 in different types of human cancer." (PMID 35274003, 2022). "Coexpression analysis revealed that KIF11, KIF18B, KIF23, and MKI67 were positively associated with the expression of IQGAP3 in all cancer types presented in the heatmap." (PMID 36164370, 2022). "Recently, multiple studies have identified strong associations between the expression of IQGAP3 and poor prognosis in various types of cancer." (PMID 32824461, 2020). "Taken together, although our results showed that IQGAP3 activated Rho and Ras, further studies are necessary to elucidate the mechanisms underlying the interactions of IQGAP3 with Rho or Ras in cancer." (PMID 32824461, 2020). "While enforced expression of IQGAP3 causes accelerated proliferation and migration/invasion of cancer cells, suppression of its expression leads to a reduction in tumorigenic potential." (PMID 24849319, 2014). "IQGAP3 is typically located between the cellular junctions of epithelial cells and is closely associated with cytoskeleton, cell proliferation, cell adhesion, vascular invasion, the invasion and metastasis of cancer cells, and the regulation of cell motility." (PMID 40634295, 2025). "High expression of IQGAP3 was also associated with a poor prognosis in some types of human cancer." (PMID 35274003, 2022). "IQGAP3 expression was associated with sensitivity to a wide array of drugs in cancer cells lines." (PMID 35274003, 2022). "The results showed that high-expressed IQGAP3 is a risk factor for various cancers, whether DFI, OS, PFI, or DSS." (PMID 36164370, 2022). "We wished to explore the gene-mutation information of IQGAP3 in human cancer types." (PMID 35274003, 2022). "IQGAP3 is often overexpressed in cancer and is implicated as an oncogene." (PMID 34068608, 2021). "Urinary levels of IQGAP3 showed good utility as a diagnostic marker that candifferentiate between BC patients and non-cancer patients with hematuria(PicoGreen-adjusted AUC, 0.910; sensitivity, 80.0%; specificity, 90.7%;RiboGreen-adjusted AUC, 0.854; sensitivity, 92.2%; specificity, 65.2%)." (PMID 29581849, 2018). "Thus, IQGAP3 urinary NA levels could be a suitablenon-invasive diagnostic tool for distinguishing those with BC from those withnon-cancer-associated hematuria." (PMID 29581849, 2018). "IQGAP3 is upregulated at the RNA level but downregulated at the protein level in all three cancers, suggesting post-transcriptional suppression." (PMID 41439026, 2025). "Two genes, IQGAP3 and TPX2, were upregulated at the mRNA level but showed protein-level downregulation (IQGAP3 in all cancers; TPX2 in BRCA and COAD, up in LUAD), indicating post-transcriptional repression." (PMID 41439026, 2025). "IQGAP3 is a critical regulator of mitotic progression and genome stability; thus, it governs proliferation and migration of numerous cancers." (PMID 38725628, 2024).
cancer (continued). "In cancer cells, IQGAP3 promotes cell migration, epithelial to mesenchymal transition (EMT), invasion and metastasis by activating TGF-β signaling." (PMID 38674130, 2024). "In these cancer cells, kaempferol effectively inhibited proliferation and promoted death while decreasing IQGAP3 expression." (PMID 38731498, 2024). "In a further exploration, an analysis of genomic patterns governing cancer drug sensitivity unveiled a significant correlation between the heightened expression of IQGAP3 and small molecules and anticancer agents." (PMID 38560572, 2024). "It was noticed that upregulating IQGAP3 expression prevented cancer cells from undergoing apoptosis." (PMID 38731498, 2024). "We have summarized the current evidence on the contribution of IQGAP2 and IQGAP3 to these different types of cancer as examples." (PMID 36831467, 2023). "The current discovery elucidated the function of IQGAP3 in cancer development and tumorigenesis and contributed to a more personalized immunotherapy in the future." (PMID 36164370, 2022). "Overall, these results suggested that the CNV of IQGAP3 was positively correlated with IQGAP3 expression in different types of human cancer." (PMID 35274003, 2022). "In summary, these results demonstrated that IQGAP3 expression was significantly correlated with sensitivity to many drugs in different cancer cell lines." (PMID 35274003, 2022). "Using various public databases, we found that IQGAP3 expression was upregulated in different types of human cancer." (PMID 35274003, 2022). "The Spearman correlation analysis revealed IQGAP3AR expression to be significantly negatively correlated with let-7c-5p expression and positively correlated with the expression of IQGAP3 in pan-cancer." (PMID 35274003, 2022). "IQGAP3 is the newest member of this family and is located at 1q21.3, a region with a high incidence of cancer spread." (PMID 36164370, 2022). "We provided, for the first time, evidence that the IQGAP3AR/let-7c-5p/IQGAP3 axis has indispensable roles in the progression and immune response in different types of human cancer." (PMID 35274003, 2022). "In pan-cancer, to evaluate the prognostic value of IQGAP3 mRNA expression levels, DSS, OS, PFI, and DFI were analyzed based on TCGA." (PMID 36164370, 2022). "IQGAP3 expression was positively correlated with sensitivity to different drugs in different cancer cell lines." (PMID 35274003, 2022). "Ultimately, we conclude that IQGAP3 is an effective prognostic biomarker for pan-cancer immune-related therapy." (PMID 36164370, 2022). "Emerging evidence has shown that IQGAP3 participates in different cancer-related signaling pathways." (PMID 35274003, 2022). "IQGAP3 expression was positively correlated with immune checkpoint–related genes in 31 cancer types." (PMID 35274003, 2022). "Studies have indicated that IQGAP3 is located mainly in chromosome 1 at 1q21.3 and has been reported to act as an oncogene in different types of human cancer." (PMID 35274003, 2022). "To ascertain the prognostic role of IQGAP3 in different types of cancer, we ascertained the OS, DFS, progression-free survival (PFS), disease-specific survival (DSS), and relapse-free survival (RFS) in human cancer types." (PMID 35274003, 2022). "We provided the first evidence to show that an IQGAP3AR/let-7c-5p/IQGAP3 axis has indispensable roles in the progression and immune response in different types of human cancer." (PMID 35274003, 2022). "A low DNA-methylation level in IQGAP3 was correlated with a better poor prognosis in different cancer types." (PMID 35274003, 2022). "IQGAP3 has important function in cancer progression and has become a potential therapeutic target as a transmembrane protein." (PMID 36164370, 2022). "In total, we provided the first evidence that a IQGAP3AR/let-7c-5p/IQGAP3 axis has indispensable roles in the progression and immune response to different types of human cancer." (PMID 35274003, 2022).